SMCO4 (single-pass membrane protein with coiled-coil domains 4)
Synonyms: C11orf75; FN5
Tractability: Antibody: UniProt predicts a signal peptide or a membrane-spanning region.
Gene: Protein-coding gene on chromosome 11 (93,478,468 to 93,543,764, reverse strand). Ensembl gene ENSG00000166002.
Subcellular location: Membrane
Gene Ontology:
Molecular function: protein binding
Cellular component: membrane
Genetic constraint (gnomAD): Loss-of-function variants: 4 observed, 3.22 expected, observed/expected ratio (o/e) 1.24, 90% interval 0.57 to 1.9. That is too few expected variants to judge how well the gene tolerates losing a copy. Missense variants: 70 observed, 81.49 expected, observed/expected ratio (o/e) 0.86, 90% interval 0.71 to 1.05. Synonymous variants: 36 observed, 35.64 expected, observed/expected ratio (o/e) 1.01, 90% interval 0.77 to 1.33.
Homologues: Orthologues: guinea pig SMCO4 (100% identical), macaque SMCO4 (100% identical), chimpanzee SMCO4 (98% identical), dog SMCO4 (98% identical), pig SMCO4 (98% identical), mouse Smco4 (97% identical), rat Smco4 (97% identical), tropical clawed frog smco4 (93% identical).
Diseases named in the same sentence as SMCO4 in open-access papers:
SMCO4 is named in the same sentence as 4 diseases in open-access papers, as found by Europe PMC text mining. Sharing a sentence is not in itself a finding about the gene and the disease. The quoted sentences say what the papers report.
breast carcinoma (1 paper, 2023). "The PHF1 protein was shown to be overexpressed, while the SMCO4 and PSMG1 proteins had medium expression levels in breast carcinoma cells, all with low tissue specificity." (PMID 38138918, 2023). "Promising proteomic markers of breast cancer (SPG7, ADRB1, SMCO4, PHF1, and PSMG1) from NPCs identified in this study should be further verified in larger patient groups." (PMID 38138918, 2023).
type 2 diabetes (1 paper, 2024). "Additionally, an eQTL associated with SMCO4 colocalises with a type 2 diabetes signal marked by rs57235767 in islets." (PMID 39240351, 2024). "It is possible that SMCO4 functions early in type 2 diabetes development or in a limited subset of cells." (PMID 39240351, 2024). "In our analysis pipeline, two genes, SMCO4 and FXR2, were among those identified as potential type 2 diabetes candidate genes in both EndoC-BH1 and prior primary beta cell chromatin maps." (PMID 39240351, 2024).
cancer (1 paper, 2023). A tumor composed of atypical neoplastic, often pleomorphic cells that invade other tissues. "The role of SMCO4 in cancer progression has not yet been reported; however, the protein is shown to be a transmembrane protein involved in cellular signaling." (PMID 38138918, 2023).
SMCO4 also shares sentences with these, for which no sentence is quoted: ovarian carcinoma (1 paper).